ZNF710 (zinc finger protein 710)
Description:
May be involved in transcriptional regulation.
Synonyms: DKFZp547K1113; FLJ37393; FLJ00306
Tractability: PROTAC: UniProt records ubiquitination sites on it.
Gene: Protein-coding gene on chromosome 15 (89,999,180 to 90,082,206, forward strand). Ensembl gene ENSG00000140548.
Subcellular location: Nucleus
Subcellular location (Human Protein Atlas): Mitochondria; Nucleoplasm
Pathways (Reactome):
Gene expression (Transcription): Generic Transcription Pathway
Gene Ontology:
Molecular function: protein binding; DNA-binding transcription factor activity; RNA polymerase II cis-regulatory region sequence-specific DNA binding
Biological process: regulation of transcription by RNA polymerase II
Cellular component: nucleus
Genetic constraint (gnomAD): Loss-of-function variants: 13 observed, 52.39 expected, observed/expected ratio (o/e) 0.25, 90% interval 0.16 to 0.4. The upper end of that interval is the gene's LOEUF score, 0.4, which puts it in group 1 of 6, group 1 being the genes least tolerant of losing a copy. Missense variants: 721 observed, 957.28 expected, observed/expected ratio (o/e) 0.75, 90% interval 0.71 to 0.8. Synonymous variants: 383 observed, 405.44 expected, observed/expected ratio (o/e) 0.94, 90% interval 0.87 to 1.03.
Homologues: Orthologues: chimpanzee ZNF710 (99% identical), pig ZNF710 (97% identical), dog ZNF710 (97% identical), rabbit ZNF710 (95% identical), rat Zfp710 (94% identical), guinea pig ZNF710 (88% identical), tropical clawed frog znf710 (72% identical), zebrafish znf710a (54% identical), zebrafish znf710b (52% identical), Drosophila melanogaster CG10631 (25% identical), Drosophila melanogaster CG11696 (17% identical), Drosophila melanogaster CG11902 (17% identical). Paralogues in human: ZNF366 (47% identical), ZNF865 (20% identical), ZNF667 (17% identical), ZNF671 (15% identical), ZNF662 (13% identical), ZNF783 (11% identical), ZNF212 (11% identical).
Diseases named in the same sentence as ZNF710 in open-access papers:
ZNF710 is named in the same sentence as 3 diseases in open-access papers, as found by Europe PMC text mining. Sharing a sentence is not in itself a finding about the gene and the disease. The quoted sentences say what the papers report.
Obesity (1 paper, 2018). Accumulation of substantial excess body fat. "Among the genes affiliated with the 119 significant CpGs, SOCS3 and DOK2 were differentially expressed in the SAT of obesity patients, while seven genes (SOCS3, PRR5L, ABCG1, BRDT, B3GNT7, ZNF710, and RARRES1) were differentially expressed in the VAT of obesity patients." (PMID 30619480, 2018).
tumor (1 paper, 2021). "There were 11 DEGs associated with tumor cell differentiation and dedifferentiation between EGFP- CD44-/CD24- cells and EGFP+ CSCs and they included RHBDL2, HIST1H4H, DSCC1, ZNF710, ATP8B3, and others." (PMID 34318746, 2021).
ZNF710 also shares sentences with these, for which no sentence is quoted: cancer (1 paper).